KIT (KIT proto-oncogene, receptor tyrosine kinase)
Diseases named in the same sentence as KIT in open-access papers (continued):
Sharing a sentence is not in itself a finding about the gene and the disease.
acute myeloid leukemia (continued). "Midostaurin (PKC412), a multitargeted tyrosine kinase inhibitor that targets FMS-related tyrosine kinase 3 and KIT, is in clinical trials for the treatment for acute myeloid leukemia and advanced systemic mastocytosis." (PMID 24085261, 2013). "This hypothesis is supported by observations in Kasumi-1 cells, which are from a human acute myeloid leukaemia cell line, wherein mutant c-KIT accumulates in TfR-positive recycling endosomes." (PMID 39833146, 2025). "We report an unusual case of de novo leukemic MCL without expression of CD25 and KIT mutations, which initially raised the suspicion of tryptase-positive (T+) acute myeloid leukemia (T+ AML) or myelomastocytic leukemia (MML)." (PMID 29458385, 2018). "HOTAIR modulated c-KIT expression through sponging miR-193a in acute myeloid leukemia." (PMID 28415631, 2017). "We report a rare case of KIT-negative SM associated with acute myeloid leukemia." (PMID 40950415, 2025). "Moreover, EVs containing KIT are increased in the serum of patients with systemic mastocytosis, a clonal disease of the huMC compartment associated with KIT variants, and in the plasma of patients with CD34+ acute myeloid leukaemia." (PMID 36239715, 2022). "Moreover, compatible with KIT regulating the expansion of EMPs with their intrinsic myeloid potential, gain-of-function mutations have been associated with human adult and pediatric core binding factor acute myeloid leukemia (CBF-AML), for which KIT mutations are poor prognostic factors." (PMID 34395414, 2021). "In cancers of the blood system, MRPL33 affects the receptor tyrosine kinase TrkA or KIT expression levels in acute myeloid leukemia (AML) and neuroblastoma, which has a prognostic value for both types of cancer." (PMID 33238645, 2020). "Based on cytokine-dependentmurine acute myeloid leukemia (AML) FDC-P1 cells, we generated a new cell linewith ectopic expression of the KIT gene encoding mutant humanreceptor tyrosine kinase (N822K)." (PMID 32477598, 2020). "We report here that the c-KIT (CD117) targeting with dasatinib and radotinib promotes acute myeloid leukemia (AML) cell death, and c-KIT endocytosis is essential for triggering c-KIT-positive AML cell death by dasatinib and radotinib during the early stages." (PMID 29127384, 2017). "Activating mutations of the class III receptor tyrosine kinase KIT are frequently found in systemic mastocytosis (SM) and core binding factor acute myeloid leukemias (CBF AML)." (PMID 29137311, 2017). "FLT3 is an RTK that drives the development of acute myeloid leukemia (AML) and is closely related to other hematopoietic RTKs including PDGFR, M-CSFR, and c-KIT." (PMID 36991452, 2023). "The prognostic significance of KIT mutations and optimal thresholds and time points of measurable residual disease (MRD) monitoring for acute myeloid leukemia (AML) with RUNX1-RUNX1T1 remain controversial in the setting of hematopoietic stem cell transplantation (HSCT)." (PMID 33477584, 2021). "MiR-193a undergoes epigenetic silencing in acute myeloid leukemia by the AML1/ETO fusion protein, where miR-193 was found to repress several pro-leukemogenic factors, including KIT." (PMID 30619488, 2018). "Another negative feedback-loop in acute myeloid leukemia (AML), bearing KIT driver mutations, involves miR-29b and NF-κB." (PMID 29601548, 2018). "In acute myeloid leukaemia (AML), KIT is expressed in at least two-thirds of cases, although the number with C-KIT mutations is much smaller." (PMID 14710199, 2004). "In acute myeloid leukemia (AML), miR-193b arrests the cell cycle at the G1/S phase and induces apoptosis by targeting multiple factors and the downstream cell cycle regulator of the KIT-RAS-RAF-MEK-ERK (MAPK) signaling pathway." (PMID 36233210, 2022).
acute myeloid leukemia (continued). "As a comparison, it has been proved that miR-137 could downregulate KIT or CXCL12 in other cancers such as small cell lung cancer, acute myeloid leukemia, and glioblastoma." (PMID 31032340, 2019). "The first two pathways that are worth mentioning are associated (i) with the ErbB receptor signaling and (ii) with genes (c-KIT, STAT3, AKT3) that have been mainly described as increased in acute myeloid leukemia, in which the crucial role of CEBPA has been widely demonstrated." (PMID 26496024, 2016). "In acute myeloid leukemia (AML), ROCK1 depletion by genetic knockout or ROCK inhibition with H-1152, Y27632, or fasudil reduced the survival of malignant cells bearing oncogenic form of KIT, FLT3, and BCR-ABL through suppressing MLC phosphorylation." (PMID 26725045, 2016). "Sorafenib, a multi-kinase inhibitor with N,N-diphenyl urea structure that can inhibit the activity of c-RAF, b-RAF, c-KIT, FLT3, PDGFR-α/β, and VEGFR-1/2/3 is usually used in tumor treatment, especially in acute myeloid leukemia (AML) clinical trials." (PMID 36558930, 2022). "Both patients were associated with a poor clinico-genetic risk profile, e.g. KIT D816V negative MCL and multimutated SM-MDS/MPNu progressing to secondary acute myeloid leukemia even more indicating DECT as a supplementary tool for identification of high-risk disease." (PMID 35987779, 2022). "We now could also demonstrate that neither midostaurin nor avapritinib had an effect on the multimutated KIT D816V negative compartment, which may lead to KIT independent resistance and progression, e.g., secondary KIT D816 negative acute myeloid leukemia." (PMID 30911112, 2019). "Here, we report a rare case of a 63-year-old male who was diagnosed with concurrent KIT-negative SM on a background of acute myeloid leukemia (AML)." (PMID 40950415, 2025). "For example, acute myeloid leukemia (AML), myeloma, and Ewing sarcoma have a substantial percentage of samples with high KIT expression, while chronic lymphoblastic leukemia (CLL) has low mean KIT expression, and no patients with CLL have high KIT expression." (PMID 35887076, 2022).
ovarian carcinoma (157 papers, 2004 to 2025). A malignant neoplasm originating from the surface ovarian epithelium. "Malignant ovarian dysgerminomas represent ∼3% of all ovarian cancers in Western countries, resembling testicular seminomas, regarding chromosomal aberrations and c-KIT mutations." (PMID 22937135, 2012). "The c‐KIT/phospho‐PHB axis has been reported to increase ovarian cancer stemness and chemoresistance via Notch3–PBX1 and β‐catenin–ABCG2 signaling." (PMID 41179704, 2025). "Exposure of sarcoma and PDX ovarian carcinoma cells to [pazopanib + entinostat] caused a prolonged activation of ERBB1 and transient/prolonged activations of ERBB2, c-KIT, and c-MET, in a cell-specific fashion." (PMID 31380285, 2019). "Consistent with this study, we observed that glucose-restricted cells exhibit increased expression of ovarian cancer stem cell markers, such as CD117 (KIT and CD44, as well as decreased expression of CA125 (MUC16)." (PMID 28412735, 2017). "In line with this, expression of pluripotency markers such as OCT4 and NANOG and the protoncogene c-KIT in stem-like cells in endometriosis have been described and related to the development of the disease and progression towards ovarian cancer." (PMID 26446766, 2015). "To investigate the relationship between miR-193a and c-KIT/E2F6 in ovarian cancer, we over-expressed miR-193a in A2780 ovarian cancer cells which have low levels of miR-193a expression." (PMID 25545504, 2014). "Although decreasing the value of k5 (associated with low estrogen level) can reduce the expression of the OCIC marker c-KIT, some clinical evidence suggests that anti-estrogen therapy is only partially effective in the treatment of ovarian cancer." (PMID 25545504, 2014). "In ovarian carcinoma, expression of KIT and PDGFRA protein has been documented, but the frequency and the molecular background of expression are poorly known." (PMID 15583695, 2004). "In ovarian carcinomas, the reported frequency of KIT and PDGFRA expression has been highly variable, and little is known about their molecular background and association with clinical parameters." (PMID 15583695, 2004). "Many reports have indicated high frequency (71–100%) of KIT expression in ovarian carcinomas, whereas others have shown lower levels of expression (0–22%)." (PMID 15583695, 2004). "KIT expression in normal ovaries and ovarian carcinomas has been addressed in several previous studies with highly variable results." (PMID 15583695, 2004). "Indeed, STAT3 and Akt/β-catenin pathways have been shown to play an important role in driving the enrichment of breast CSCs, and β-catenin has been demonstrated to mediate the effect of KIT on promoting stemness of ovarian cancer." (PMID 34718356, 2022). "Studies in ovarian cancer cells have related c-KIT expression to cancer stemness." (PMID 35490363, 2022). "The mutation frequencies for NF1, RB1, and KIT in our BM samples were not in the range described for ovarian cancer specimens, they were less frequent." (PMID 28497333, 2017). "Although imatinib has shown limited clinical benefit as a single agent in ovarian cancer, it is well tolerated, and its ability to inhibit c-KIT and block IDO expression suggests imatinib has potential to alleviate suppression as an adjuvant to tumor vaccination." (PMID 26343197, 2015). "Importantly, a positive correlation of E2F6 and c-KIT is only observed in ovarian cancer patients with low EZH2 expression." (PMID 25545504, 2014). "It has been experimentally demonstrated that a microRNA, namely miR-193a, targets c-KIT mRNA for degradation and could play a crucial role in ovarian cancer development." (PMID 25545504, 2014). "Although imatinib has shown minimal clinical benefit as a single agent in ovarian cancer, it is well tolerated, and its ability to inhibit c-KIT and block IDO expression suggests imatinib has potential to alleviate immune suppression as an adjuvant treatment for DC vaccination." (PMID 24302925, 2013).
ovarian carcinoma (continued). "The real biological role of KIT in ovarian carcinoma cells remains to be clarified." (PMID 15583695, 2004). "As regards KIT, our finding extends the previous observation of no mutations in 50 ovarian carcinomas of different histological types." (PMID 15583695, 2004). "Thus, the reversible/irreversible feature of c-KIT mRNA regulation processes by different E2F6 inhibition strength can partially explain the clinical observation that anti-estrogen therapy is only partially effective in the treatment of ovarian cancer." (PMID 35216394, 2022). "Similarly, the transcription factor E2F6 can also function as a ceRNA, inhibiting the effects mediated by the tumor suppressor miR-193a and promoting the stemness of ovarian cancer cells (HeyC2) through the upregulation of the ovarian cancer stemness marker c-KIT." (PMID 34439740, 2021). "Moreover, ovarian cancer may be caused by ovarian cancer-initiating cells characterized by surface antigen CD44 and the ovarian CSC maker c-KIT (CD117)." (PMID 33014829, 2020). "Although little is known about the function of KIT in ovarian cancer cells, the inhibition of KIT expression under thyrostimulin treatment might contribute to a reduction in KIT-mediated growth control and thus further promote ovarian cancer progression." (PMID 27273257, 2016). "Secondly, the top six genes, each with more than 100 publications (KIT, EGF, STAR, GAL, FGF2, VIP), have known established roles in ovarian cancer." (PMID 40699804, 2025). "Increased expression of CSC markers and transcription factors, such as CD44, KIT Proto-Oncogene (KIT, CD117), POU Class 5 Homebox 1 (POU5F1, OCT4), and NANOG, was observed in ovarian cancer cells treated by cisplatin or paclitaxel both in vitro and in vivo." (PMID 35401749, 2022). "Results from the PPI network revealed that the KIT, TOP2A, and MYB genes exhibited a higher correlation with other genes, and were thus likely to affect the development of ovarian cancer." (PMID 33407591, 2021). "Using an integrated analysis of proteomic and transcriptomic data, we have observed the positive regulation of proliferation/stemness factors (e.g., cyclins-CDKs and KIT) and negative regulation of MMPs (e.g., MMP1 and MMP7) by CD83 in ovarian cancer cells." (PMID 32823589, 2020). "Consistent with this transcriptomic observation, proteomics identified that KIT was attenuated, whereas MMP1 and MMP7 were elevated in CD83-KD ovarian cancer cells." (PMID 32823589, 2020). "Ovarian cancer stem cells (CSCs), also known as cancer-initiating cells, are characterized by cell surface expression of CD24, CD44, CD117 (KIT), SOX2, and NANOG." (PMID 32823589, 2020). "In PDX isolates of ovarian cancer cells, however, the expression and phosphorylation of ERBB1, ERBB2, c-MET, c-KIT, and c-SRC was reduced by drug combination exposure." (PMID 31380285, 2019). "AKT, which is strongly activated by oncogenic KIT, was found to stabilize XIAP in AKT-transfected human ovarian cancer epithelial cell line A2780S and human embryonic kidney (HEK) 293 cells." (PMID 27167336, 2016). "Expression of miR-193a resulted in a significant down-regulation of c-KIT mRNA and E2F6 mRNA, thus suggesting that c-KIT mRNA and E2F6 mRNA are targets of miR-193a in ovarian cancer cells." (PMID 25545504, 2014). "KIT (CD117)+ ovarian cancer cells manifest a striking higher tumorigenic activity than CD117-negative cancer cells and were able to generate the original tumor heterogeneity, suggesting self-renewal and multi-linage differentiation capabilities of these cells." (PMID 37189618, 2023). "Another study showed that the expression of EZH2 was positively correlated with c-KIT (CD117), a surface marker of EOCSCs, and that EZH2 inhibition may represent an effective therapeutic strategy against ovarian cancer." (PMID 33408782, 2021).
ovarian carcinoma (continued). "A phase II clinical trial to determine the effectiveness of imatinib, a PDGFR and KIT inhibitor, in patients with refractory ovarian cancer has been completed (NCT00039585) with no results posted to date." (PMID 29503809, 2018). "Other multifunctional kinase inhibitors that may be effective therapeutic agents for ovarian cancer include pazopanib (targets VEGFR, PDGFR, FGFR, and KIT), sunitinib (targets VEGFR, PDGFR, FLT3, and KIT), and sorafenib (targets VEGFR, PDGFR, and RAF kinases)." (PMID 29503809, 2018). "Additional analysis of the TCGA ovarian cancer dataset demonstrates that ovarian cancer patients with low expression of EZH2, a polycomb-group family protein, show positive correlation between E2F6 and c-KIT." (PMID 25545504, 2014). "Our previous study has shown that ovarian cancer may be initiated by ovarian cancer initiating cells (OCIC) characterized by surface antigen CD44 and c-KIT (CD117)." (PMID 25545504, 2014). "Interestingly, ovarian cancer patients with low EZH2 level show a positive correlation between the expression of E2F6 and c-KIT." (PMID 25545504, 2014). "Of note, no ovarian cancer patients within any stratum exhibited ALK rearrangement, BRAF, EGFR, or KIT mutations." (PMID 25593979, 2014). "Moreover, this study demonstrated that the small subpopulation of stem-like, tumor-propagating ovarian cancer cells were earmarked by expression of cluster of differentiation 44 (CD44) and other stem cell and EMT markers such as KIT (CD117), SCF (stem cell factor), SLUG (SNAIL2), and VIM (vimentin)." (PMID 31614568, 2019). "Downstream of c-KIT, MK-2206 and ipatasertib/GDC-0068 are potent and highly selective pan-AKT inhibitors, and both are currently in multiple phase 2 trials (clinicaltrials.gov NCT01802320, NCT02162719, NCT01776008), including treatment of ovarian cancer (NCT01283035)." (PMID 26343197, 2015). "Taken together, these mechanisms may lead to a non-reversible expression of c-KIT and activation of the cell growth signaling in ovarian cancer." (PMID 25545504, 2014). "Importantly, this is also consistent with the clinical evidence that the expression of E2F6 and c-KIT are correlated in ovarian cancer patients with low expression of EZH2 but not in cases of high EZH2 expression." (PMID 25545504, 2014). "Furthermore, the consistent expression of KIT and PDGFR receptors and their ligands was seen in a phase II trial in women with ovarian cancer, together with the absence of mutations in these genes and with lack of response to imatinib." (PMID 23497641, 2013). "While not specifically studied in MCs, a connection with KIT, the principal receptor tyrosine kinase of MCs, was recently reported, whereby KIT activation in ovarian cancer stem cells could stabilize Notch Receptor 3 (NOTCH3) and thereby increase the downstream target PBX1." (PMID 36142795, 2022). "The same experiment was also repeated on other cell lines where c-KIT is not responsible for growth, i.e. TOV112 ovarian cancer cells and KARPAS299 lymphoma cell line and data corroborated those obtained with PC3 cell line (data not shown)." (PMID 26942875, 2016). "KIT and PDGFRA are not ubiquitous proteins, but their expression has also been reported in some epithelial malignancies including in ovarian carcinoma." (PMID 15583695, 2004).